ANO3 (anoctamin 3)
Diseases named in the same sentence as ANO3 in open-access papers:
ANO3 is named in the same sentence as 65 diseases in open-access papers, as found by Europe PMC text mining. Sharing a sentence is not in itself a finding about the gene and the disease. The quoted sentences say what the papers report.
Dystonia (39 papers, 2013 to 2025). An abnormally increased muscular tone that causes fixed abnormal postures. "Dystonia is a common neurological hyperkinetic movement disorder that can be caused by mutations in anoctamin 3 (ANO3, TMEM16C), a phospholipid scramblase and ion channel." (PMID 39773217, 2025). "Progressive dystonia was associated with ANO3 and a microdeletion in Xp11.4 including the CASK gene, whereas progressive athetosis was seen with ATM and TWNK." (PMID 40326640, 2025). "Other well-established genes associated with isolated dystonia include ANO3 and GNAL, both typically linked to autosomal dominant, adult-onset craniocervical or segmental dystonia." (PMID 40584247, 2025). "Like ANO3 variants, mutations in hippocalcin were shown to contribute to the appearance of dystonia." (PMID 39773217, 2025). "In our previous study, we determined intracellular Ca2+ concentrations ([Ca2+]i) in skin fibroblasts isolated from patients with dystonia and in HEK293 cells overexpressing dystonia-causing ANO3 variants (V561L, S651N, A599D, and S116L)." (PMID 39773217, 2025). "ANO3-linked dystonia has an autosomal-dominant inheritance pattern, yet only heterozygous variations have been identified." (PMID 38612382, 2024). "Currently, genes THAP1, GNAL, TOR1A, and ANO3 are linked to isolated dystonia and have undergone extensive validation." (PMID 38612382, 2024). "Both its mutation and the ANO3 mutation are associated with myoclonus‐dystonia.Although both ITPR3 and CACNA1B act on cytoplasmic calcium ion concentration, the specific effects of these mutations have not been confirmed in vivo, warranting further study." (PMID 37649308, 2023). "Within the dystonia cohort, only a single ANO3 loss of function variant was observed, associated with a documented cervical dystonia phenotype, but not previously reported." (PMID 35925398, 2022). "The single variant (loss of function) identified within the dystonia cohort (ANO3) was linked with a clinical diagnosis of cervical dystonia and has not been previously reported (highlighted in bold)." (PMID 35925398, 2022). "Other genes found to be associated with isolated or combined dystonia include ANO3 (DYT24), TUBB4A (DYT4), GCH1 (DYT5a), TH (DYT5b), TAF1 (DYT3), PRKRA (DYT16), ATP1A3 (DYT12), SGCE (DYT11), KCTD17, and CACNA1A." (PMID 33051750, 2021). "ANO3 pathogenic variants have a dominant effect on dystonia, and some have been associated to a complex neurological syndrome combining dystonia and myoclonus phenotypes." (PMID 33557955, 2021). "We conclude that DBS is likely to result in a successful but partial response in dystonia due to ANO3 mutations, but large case series are needed." (PMID 33488508, 2020). "Another patient with an ANO3 mutation (p.Glu510Lys) had a substantial improvement in dystonia and tremor but in this case myoclonus persisted." (PMID 33488508, 2020). "In summary, our study expands the mutational and clinical spectrum of DYT24 due to ANO3 mutations in dystonia." (PMID 32116979, 2019). "Description of ANO3 variants identified in 187 dystonia cases, disease characteristics, and predictive pathogenicity." (PMID 32116979, 2019). "The interpretation of variants in ANO3 remains difficult, thus demanding further functional studies to better understand the role of ANO3 in dystonia." (PMID 32116979, 2019). "Dystonia 24 was first reported in 2000 as an autosomal dominant cause of dystonia caused by variants in the ANO3 gene." (PMID 30455893, 2018). "Of note, both sporadic and familial cases of ANO3-related cervical dystonia have been observed in the literature highlighting the reduced penetrance associated with this form of dystonia." (PMID 27919237, 2016). "Patients with familial cervical dystonia who also have myoclonus-dystonia as well as patients with prominent tremor and mild dystonia should be tested for ANO3 mutations." (PMID 24442708, 2014).
Dystonia (continued). "We previously reported patients that were heterozygous for the ANO3 variants S651N, V561L, A599D and S651N, which cause dystonia by unknown mechanisms." (PMID 39773217, 2025). "Dysregulated Ca2+ signaling by ANO3 variants may impair the activation of K+ channels in striatal neurons of the brain, thereby causing dystonia." (PMID 39773217, 2025). "Additionally, a previous study has reported an infantile-onset patient manifested dystonia, parkinsonism, and developmental regression, caused by a de novo missense variant in ANO3." (PMID 37304079, 2023). "In accordance with the scientific literature, we detected potentially relevant variations in known genes previously associated with CD and BSP, such as CIZ1, GNAL, and ANO3, and in other dystonia-related genes, such as KMT2B, VPS16, and KCNN2, for a total of nine patients." (PMID 37445923, 2023). "A single loss of function variant (ANO3) was identified in the dystonia cohort." (PMID 35925398, 2022). "With the emerging application of NGS screening technologies in movement disorders, this study aims to screen ANO3 mutations in inherited or idiopathic dystonia by NGS to identify ANO3 variants in Chinese patients with dystonia and to expand the phenotypic and genotypic spectrum of DYT24." (PMID 32116979, 2019). "In our study, ANO3 variants were found in 2.1% of clinically suspected idiopathic or inherited dystonia patients, which indicated that this type of dystonia might be rare in Chinese patients." (PMID 32116979, 2019). "Rare ANO3 variants seem to represent an uncommon cause of dystonia in China." (PMID 32116979, 2019). "In addition, we observed heterogeneity in both genotypes and phenotypes in DYT24 caused by ANO3 mutations in Chinese dystonia patients." (PMID 32116979, 2019). "Rare ANO3 variants appear to represent an uncommon cause of dystonia in China." (PMID 32116979, 2019). "Other dystonia genes with likely pathogenic or pathogenic variants were EIF2AK2 (n = 5 index patients), ANO3 (n = 2), EIF4A2 (n = 1), and TOR1A (n = 1) for genes causing isolated dystonia." (PMID 40533913, 2025). "The present data now provide a direct connection between mutations in ANO3, loss of plasma membrane expression of ORAI1, disturbed Ca2+ signaling, and dystonia." (PMID 39773217, 2025). "Genetic dystonias encompass both situations where the primary symptom is dystonia (e.g., TOR1A, ANO3 mutations, etc.)and conditions where dystonia is a co-occurring feature of a more complex condition." (PMID 38612382, 2024). "Dystonia topography revealed prominent upper‐body distribution in most of our patients, reminiscent of the clinical pictures associated with other dystonia‐related genes, such as GNAL20, 21 or ANO3." (PMID 35722775, 2022). "The classical distinction is very hard to differentiate between isolated and combined dystonias since many genes have been shown to determine multiple dystonic presentations (e.g., ANO3, GNAL, ADCY5, and ATP1A3)." (PMID 36705216, 2022). "However, it remains unclear how ANO3 mutations cause dystonia at a mechanistic level." (PMID 32116979, 2019). "The identification of the ANO3 gene needs to be confirmed from independent studies, which also would allow an estimation of its frequency compared with other dystonia genes." (PMID 24442708, 2014). "ANO3-related dystonia often presents with prominent tremor and involvement of the laryngeal or facial muscles, while GNAL variants more commonly cause cervical dystonia that may spread to adjacent regions." (PMID 40584247, 2025). "To date, missense mutations are the most commonly reported mutation type in relation to ANO3-dystonia pathology, with no previously reported loss of function mutations in this context." (PMID 35925398, 2022).
Dystonia (continued). "Further functional studies are needed to better understand the role of ANO3 in dystonia." (PMID 32116979, 2019). "Recent advances in genetic techniques have allowed the recognition of an increasing number of genes underlying dystonia, but most of the genes discovered in the past 4 years seem to be almost exclusively found in adult-onset cases (e.g., GNAL, ANO-3) and are apparently a very rare cause of dystonia." (PMID 28066314, 2016). "Importantly, the phenotypes associated with mutations in the DYT genes enriched in the putamen ‘cyan’ module belonged to different clinical subtypes of dystonia, namely isolated dystonia (ANO3 and HPCA), combined dystonia (KCTD17 and ADCY5), and paroxysmal dystonia (KCNA1, CACNA1A, PRRT2 and SCN8A)." (PMID 32889528, 2020). "Thus, screening ANO3 mutations in dystonia patients without focal dystonia or family histories of dystonia may assist in expanding the diagnostic spectrum of DYT24." (PMID 32116979, 2019). "Additional isolated dystonia loci include DYT23 (CIZ1), DYT24 (ANO3), and DYT25 (GNAL), all of which have recently been extensively reviewed." (PMID 29110692, 2017). "Like these, other dystonia loci such as DYT23 (CIZ1) and DYT24 (ANO3) are yet to be independently confirmed." (PMID 29110692, 2017). "In familial cases with dystonia and tremor with or without neuropsychiatric problems, DYT24 (Anoctamin-3 (ANO3) mutation), DYT3 (Lubag’s disease), and Wilson’s disease should be considered." (PMID 38708334, 2024). "With the discovery of novel dystonia genes, such as GNAL, ANO3, KCTD17, and KMT2B, these subtypes can now be allocated to the realm of inherited forms of dystonia." (PMID 33604773, 2021). "Sequencing of the other known PTD genes (THAP1, TUBB4a, CIZ1, ANO3, and GNAL) should be considered in patients with predominant cranial-cervical and laryngeal involvement, especially if family history is positive, with prioritization according to the age at onset and distribution of dystonia." (PMID 23596437, 2013).
Dystonia 24 (5 papers, 2016 to 2025).
Tremor (4 papers, 2014 to 2025). An unintentional, oscillating to-and-fro muscle movement about a joint axis. "In particular, numerous monogenic neurodegenerative, neuropathic and metabolic diseases manifest with tremor often accompanied by signs of other movement disorders, especially of a dystonic (e.g. ANO3, SGCE), ataxic (e.g. PPPP2R2B, ATX3, TBP) or parkinsonian (e.g. LRRK2, FMR1, ATX3) type." (PMID 39346806, 2024). "Some of the patients with ANO3 mutations were affected by tremor as the sole initial manifestation without or (later) with very mild dystonic posturing that was misdiagnosed as ET." (PMID 24442708, 2014).
breast carcinoma (3 papers, 2020 to 2022). "This analysis has revealed a number of intact transcripts that are massively upregulated by recurrent geneUIB fusions, including IGF2 in colorectal, ETV1 in prostate, IGF2BP3 in thyroid, and ANO3, LIPG, FUT5, and RSG9 in breast cancers (ordered by the expression fold change within a tumor type)." (PMID 32631391, 2020).
focal dystonia (3 papers, 2019 to 2025). A dystonia that is localized to a specific part of the body. "Among them are variants located near ANO3, a gene that encodes anoctamin‐3, a transmembrane protein that belongs to a family of calcium‐activated chloride channels and is implicated in focal dystonia, particularly craniocervical." (PMID 39046104, 2024). "The phenotypic heterogeneity indicates that it is insufficient to just assess ANO3 mutations in focal dystonia, and emerging sporadic ANO3 variants raise attention to patients without family history." (PMID 32116979, 2019).
Alzheimer disease (2 papers, 2022). A progressive, neurodegenerative disease characterized by loss of function and death of nerve cells in several areas of the brain leading to loss of cognitive function such as memory and language. "Finally, ANO3 is significantly differentially expressed in relation to Alzheimer’s disease." (PMID 36304274, 2022).
Charcot-Marie-Tooth disease (2 papers, 2021 to 2022). An inherited degenerative disorder involving the peripheral nerves. "The ANO3 missense variant c.638C>T was reported in ClinVar as VUS without phenotype and TRPV4 c.2336+1G>A as VUS for Charcot-Marie-Tooth disease." (PMID 35806193, 2022).
Cluster headache (2 papers, 2019 to 2025). A type of headache characterized by repeated attacks of unilateral pain lasting 15 to 180 minutes and associated with local autonomic signs. "Lastly, they expanded their analysis to include ANO3, ITGAL, PLCE1, and PCDHB6 genes and found rs1531394 in the ANO3 gene to be significantly associated with cluster headache." (PMID 39560176, 2025). "We discovered a significant association between anoctamin 3, a gene encoding a calcium-activated ion channel, and cluster headache." (PMID 31366133, 2019).
essential tremor (2 papers, 2014 to 2016). A relatively common disorder characterized by a fairly specific pattern of tremors which are most prominent in the upper extremities and neck, inducing titubations of the head. "ANO3 mutations were reported in a spectrum of dystonic patients initially presumed to have familial essential tremor." (PMID 27881096, 2016). "Tremor was the sole initial manifestation in some individuals with ANO3 mutations, leading to misdiagnosis as essential tremor." (PMID 24442708, 2014).
generalized dystonia (2 papers, 2025). "In our previous study, we presented data on novel, i.e. previously unreported, and known ANO3 variants causing childhood-onset generalized dystonia." (PMID 39773217, 2025).
idiopathic dystonia (2 papers, 2019 to 2022). "The ANO3 c.3100G>C variant is present in the Human Gene Mutation Database (HGMD) and described as likely disease-causing with questionable pathogenicity in primary torsion dystonia." (PMID 36430572, 2022).
mumps (2 papers, 2018 to 2022). "TMEM16C (ANO3) is associated with childhood mumps and rubella vaccination-related febrile seizures." (PMID 29866033, 2018).
Seizure (2 papers, 2015 to 2021). A seizure is an intermittent abnormality of nervous system physiology characterized by a transient occurrence of signs and/or symptoms due to abnormal excessive or synchronous neuronal activity in the brain. "The variant associated with the highest risk of febrile seizures was in the anoctamin 3 (ANO3) gene, which encodes a transmembrane protein that belongs to a family of chloride channels, and the fourth locus was an intergenic region on chromosome 12q21.33." (PMID 26302787, 2015).
autism spectrum disorder (1 paper, 2016). A spectrum of developmental disorders that includes autism, and Asperger syndrome. "No nonsense or frame-shift mutations in ANO3 have been reported in association with DYT24, however there are several rare frameshift and nonsense variants present in ExAC, suggesting that there may be additional phenotypes associated with this gene such as autism spectrum disorders." (PMID 27919237, 2016).
Dysarthria (1 paper, 2023). Dysarthric speech is a general description referring to a neurological speech disorder characterized by poor articulation. "One male patient with the c.2276-6T>C ANO3 splice region variant has had CD (left-sided torticollis, right-sided laterocaput, and mild retrocollis) and dysarthria since the age of 41." (PMID 37445923, 2023).
thyroid cancer (1 paper, 2020). "We detect a number of recurrent fusions, such as those involving ANO3, RGS9, FUT5, CHI3L1, OR1D4, and LIPG in breast; IGF2 in colon; ETV1 in prostate; and IGF2BP3 and SIX2 in thyroid cancers." (PMID 32631391, 2020).
cancer (5 papers, 2017 to 2025). A tumor composed of atypical neoplastic, often pleomorphic cells that invade other tissues. "Pathways associated with cancer are also enriched in the C+/+/Tia1−/− testis, and the genes Psrc1, Ano3 and Zfp365, all upregulated in C+/+/Tia1−/− testis, are regulated by the tumor suppressor p5368–70." (PMID 28775379, 2017). "Anoctamin 3 (ANO3) was another downregulated genes whose paralogue ANO1 is a known cancer marker for head and neck squamous carcinoma." (PMID 38038766, 2024). "Notably, genes such as ANO3 and CTHRC1 emerged as novel contributors to pan-cancer metastasis, with their expression levels showing a direct correlation." (PMID 39748426, 2025). "In epithelial cells, ANO3 and FGP4 were identified as key drivers of metastasis and may represent novel therapeutic targets across cancers." (PMID 39748426, 2025).
tumor (4 papers, 2020 to 2025). "CTHRC1 and ANO3 were shown to be highly expressed in metastatic tumours compared to primary tumours." (PMID 39748426, 2025). "In contrast to tumors, the adjacent non-tumor tissues harbored eight genes with recurrent HBV integration, including FN1, DCC, OAZ2, ANO3, ENOX1, GRIK4, NPAT, and SNCAIP." (PMID 34209079, 2021).
movement disorder (3 papers, 2019 to 2025). Neurological conditions resulting in abnormal voluntary or involuntary movement, which may impact the speed, fluency, quality and ease of movement. "The patient with the ANO3 variant S116L had no baseline movement disorder or any developmental problems, apart from paroxysmal dystonia in the lower limbs and a mild intellectual disability." (PMID 39773217, 2025).
neurological diseases (3 papers, 2016 to 2023). "The SNP on CFA21 is located within ANO3, which has primarily been associated with neurological disease, but is also positioned in the proximity of LGR4, which is associated with cataract development in mice." (PMID 37118843, 2023). "Given that ion channels are crucial components of cellular exciting ability and are involved in many neurological diseases, for example, ANO3, whose mutations have detected in sporadic CD, functions as calcium activated chloride channels which modulate neuronal excitability." (PMID 27239368, 2016).
kidney disease (1 paper, 2025). "Notably, previous CKD genetic studies have seldom implicated ANO3, making our finding a novel insight, though related chloride channel genes such as ANO9 have been linked to kidney disease risk, highlighting the broader importance of electrolyte transport pathways." (PMID 41322097, 2025).
ANO3 also shares sentences with these, for which no sentence is quoted: Myoclonus (6 papers); cervical dystonia (4); epilepsy (4); Ataxia (3); limb-girdle muscular dystrophy (3); genetic diseases (2); Onset (2); Parkinsonism (2); rubella (2); Scott syndrome (2); Arnold-Chiari malformation (1); asthma (1); Athetosis (1); autism (1); bleeding disorders (1); borrelia (1); cerebellar ataxia (1); cognitive decline (1); developmental delay (1); eczema (1); Fragile-X tremor ataxia syndrome (1); gnathodiaphyseal dysplasia (1); gout (1); hearing loss (1); hyperekplexia (1); Hypertension (1); Hyperthermia (1); inherited dystonia (1); Intellectual disability (1); Klinefelter syndrome (1).
A further 14 diseases each share a sentence with ANO3 in 1 paper.